IL6 (interleukin 6)
Diseases named in the same sentence as IL6 in open-access papers (continued):
Sharing a sentence is not in itself a finding about the gene and the disease.
tumor (continued). "The main mechanism involves the activation of HIF-1α or oncogenes (such as RAS) by hypoxia or inflammatory factors (such as IL-6 and TNF-α) in the tumor microenvironment, leading to the secretion of VEGF, mainly VEGF-A." (PMID 40438141, 2025). "On the other hand, the IL-6-/ERK pathway was shown to be one of the key activators of cell proliferation, cancer cell growth, and tumor progression 64,65." (PMID 39975921, 2025). "M1-type macrophages in the tumor microenvironment can activate immune cells by secreting pro-inflammatory factors (TNF-a, IL-1, IL-6), enhancing anti-tumor immunity." (PMID 40557160, 2025). "Specifically, IL-6 induces an immunosuppressive state via the JAK1/STAT3 pathway, which inhibits cytotoxic T-cell differentiation and anti-tumor activity." (PMID 41019062, 2025). "Strong associations with grade ≥ 3 CRS were further observed with peak CAR T cell levels normalized to tumor burden (SPD), IL-6 peak, IL-2 AUC, and IL-1RA AUC." (PMID 40536814, 2025). "Beyond metabolites and ECM, CAFs secrete a wide array of growth factors (HGF, FGF, IGF), cytokines (IL-6, IL-8, CXCL12), and exosomes that deliver pro-survival signals directly to EC tumor cells." (PMID 40746533, 2025). "Upregulated miR-21 is transcriptionally activated by IL-6 via STAT3 and promotes tumorigenesis by targeting the tumor-suppressor PTEN, thereby enhancing PI3K/Akt signaling and sustaining NF-κB activity." (PMID 40943532, 2025). "Concurrently, we observed marked upregulation of multiple pro-tumor factors, including MMP-11, IL-6, IL-1β, CCL5, and CCL2." (PMID 41276817, 2025). "In the context of tumourigenesis, cells within the tumour ecosystem produce cytokines, chemokines, growth factors, and other molecules, such as TGF-β, monocyte chemoattractant protein 1, IL-6 and IL-8, Tumour Necrosis Factor TNF-β, CXCL-1, and VEGF." (PMID 41009413, 2025). "Preclinical studies suggest volatile anesthetics may promote tumor progression by triggering pro-inflammatory signaling, while propofol shows potential antitumor properties through immune-preserving effects and reductions in IL-6 and other inflammatory markers." (PMID 39597826, 2024). "Interleukin 6 (IL‐6) and tumor necrosis factor α (TNF‐α) were positively correlated numbers of tumor cells, indicating that the amount of CpG release was dependent on the number of tumor cells." (PMID 38145350, 2024). "Pentacyclic triterpenoids modulate inflammatory pathways by downregulating pro-inflammatory cytokines, such as IL-6 and TNF-α, thereby mitigating the chronic inflammation that drives tumor progression." (PMID 39861671, 2024). "The demethylase FTO has been shown to be responsible for decreasing m6A methylation of Apolipoprotein E (APOE) mRNA and modulating the IL-6/JAK2/STAT3 signaling pathway, thereby inhibiting tumor glycolysis and abrogating tumor growth." (PMID 38902779, 2024). "TAMs secrete a series of cytokines and inflammatory factors such as TGF-β), IL-6, IL-10, IL-13, IL-4 and TNF-α that promote tumour initiation, growth, metastasis, angiogenesis, proliferation and chemoresistance in HCC (Ref." (PMID 39320855, 2024). "For example, TAM-derived IL-6 can activate the JAK-STAT3 pathway, which promotes the survival and proliferation of tumor cells during the development of inflammation-related CRC." (PMID 38229160, 2024). "As a natural small molecule inhibitor of the IL-6/JAK2/STAT3 pathway, ginsenoside Rh2 shows great potential as an anti-tumor agent." (PMID 39845783, 2024). "IL-6 has been shown to promote angiogenesis indirectly by stimulating the production of VEGF and other angiogenic factors from both tumor cells and stromal cells within the tumor microenvironment." (PMID 38672182, 2024).
tumor (continued). "EVs originating from tumor cells often contain pro-inflammatory cytokines and chemokines, including TNF-α, IL-6, and IL-1β." (PMID 38802952, 2024). "The ERO1α/IL-6/STAT3/SLC7A11 pathway is crucial for mTORC1-mediated ferroptosis resistance and tumor growth, and combining ERO1α inhibition with ferroptosis inducers is a novel and effective treatment for mTORC1-related tumors." (PMID 38610018, 2024). "To explore the involvement of the JAK pathway in the emergence of the SCA1+ population, we treated tumor cells with a JAK inhibitor (ruxolitinib) during exposure to recombinant OSM and IL-6." (PMID 38236642, 2024). "Pan-iCAFs are linked to inflammation and secrete high levels of proinflammatory cytokines, such as IL-6, IL-8, and CXCL12, which activate inflammatory responses, promote tumor malignancy, and suppress effective antitumor immunity." (PMID 39835122, 2024). "It is, however, known that CAFs regulate and enable the pro-tumor activity of TME immune cells both directly and indirectly via the ECM and secretion of cytokines such as IL-6." (PMID 38279300, 2024). "The immune genes CXCL1, CXCL2, IL1B, IL6, CXCL8, PTGS2, and SPP1 demonstrated elevated expression levels in tumor tissue (TU) relative to all other tissues, thus validating the results obtained from the NanoString analysis (Supplementary 1)." (PMID 38979413, 2024). "IL-6 can activate STAT3, and IL-6 is often elevated systemically and in the tumor microenvironment in patients with cancer." (PMID 38611065, 2024). "DNA damage activates STING signaling, and STING-mediated activation of NF-κB enhances IL-6-mediated STAT3 expression in TNBC cells, thereby inducing tumor cell survival and immunosuppression." (PMID 39464890, 2024). "High levels of cytokines and angiogenesis‐stimulating growth factors, such as IL‐6, IL‐8, βFGF, FGF‐2, PDGF, VEGF, TGFβ, and angiopoietin, are released by MSCs, thereby promoting tumor angiogenesis." (PMID 39070181, 2024). "Tumor dimensions exhibited strong correlations with IP-10 and MIP-1 in both aqueous and vitreous humor, but Fms-related tyrosine kinase 3 ligand (FLT3LG), IL-6, IL-8, and MCP-1 showed positive relationships solely in vitreous humor." (PMID 39596556, 2024). "In the early stages of tumorigenesis, multiple signals in the TME, such as IL-6, TNF-α, and chemotactic protein-2 (CCL2), prompt monocytes to migrate to tumor tissues, where they differentiate into TAMs." (PMID 39697553, 2024). "This suggests that IL-6 and NLR have more significant value in postoperative monitoring of LCA patients and tumor recurrence." (PMID 38903721, 2024). "It induces cytokines such as IL-6 and VEGF, facilitating tumor cell proliferation and vascularization." (PMID 39766123, 2024). "The expression of tumor-promoting genes was higher in macrophages polarized with WT EVs than KO EVs, while the expression of TNF and IL6 was reduced." (PMID 38937789, 2024). "The 16-biomarker panels were divided into three categories of inflammatory markers (SAA, CRP, NLR, PLR, and LDH), TH1/TH2 cytokines (IL-2, IL-4, IL-5, IL-6, IL-8, IL-10, IFNγ, TNF, and GM-CSF), and HCC tumor markers (AFP and PIVKA-II)." (PMID 38409200, 2024). "IL‐6 secreted from CRP‐stimulated HMDMs also induced STAT3 activation in both HMDMs and tumor cells." (PMID 39564003, 2024). "Other cytokines, such as IL-17A, TNF-α, and IL-6, activate NF-kappa β and signal transducer and activator of transcription 3 (STAT3), inducing tumor growth." (PMID 39456655, 2024). "It has been well established that IL-6 and STAT3 are required for survival and proliferation of tumor-initiating intestinal epithelial cells." (PMID 38520006, 2024). "Our findings unveiled a significant upregulation in a variety of cytokines in UPP1-overexpressing tumor cells, including TGF-β1, GM-CSF, IL-1β, IL-6, IGFBP-3, CXCL5, CCL20, and VEGF, with TGF-β1 being the most prominently elevated." (PMID 38331898, 2024).
tumor (continued). "Inhibiting IL-6 also increased NK- and T cell-mediated killing of human osimertinib-resistant EGFR-mutant NSCLC tumor cells in cell culture." (PMID 39015563, 2024). "Lastly, TAM5, enriched in the primary tumor (PT), exhibited high expression of various immunosuppressive factors, including IL1A, IL1B, IL1RN, and IL6." (PMID 39236316, 2024). "Our assays of wild-type and tumor-bearing mice showed that MHV68 infection induced Type 17 inflammation, with a marked induction of IL-6." (PMID 39338937, 2024). "Tumor volume was positively correlated with levels of CXCL8 (r = 0.18, P = 0.037) and IL6 (r = 0.28, P = 0.004)." (PMID 38965454, 2024). "Alternative strategies target tumor-derived extracellular vesicles (EVs) carrying pro-angiogenic factors such as VEGF, IL-6, microRNAs which stimulate EC functions or mediate drug resistance." (PMID 38426109, 2024). "Targeted proteomics identified IL-6 and M-CSF as dominant drivers, and we show that IL-6R and CSF1R inhibition prevents tumor-induced CD14+ cDC2s." (PMID 38242119, 2024). "NT5E (CD73), CSF ligands, CD274 (PDL1), IL1B, IL6, and IL10 transcripts were primarily found in the peri necrotic zone, whereas NOS2 (iNOS), TGFB2, and NOX1 expression is localized to cellular tumor regions." (PMID 39272914, 2024). "cDC-2 express various markers such as IRF4, CD11b, SIRPα, CLEC10A, and CD1C, and produce IL-1β, IL-6, IL-8, IL-12, TFN-α, CCL3, and CXCL8 to activate anti-tumor T cell responses." (PMID 38533507, 2024). "The IL6-JAK-STAT3 signaling cascade in TNBC is known to regulate angiogenesis, tumor cell invasion, metastasis, and therapeutic resistance in TNBC." (PMID 38315147, 2024). "As is well known, IL-6 can mediate inflammatory responses, whereas TNF-α is central to coordinating inflammatory immune responses, reflecting direct changes in the tumor microenvironment." (PMID 39065602, 2024). "IL6, an inflammatory cytokine released by immune cells, links CD8+ Teff trafficking across tumor vessels to antigen-specific tumor apoptotic targets." (PMID 38813086, 2024). "Key downstream factors of NF-κB such as IL-6 and cyclooxygenase-2 (COX2) not only play critical roles in tumor initiation and progression under the influence of NF-κB but are also involved in STAT3 activation." (PMID 39493763, 2024). "These macrophages produce significant levels of cytokines such as transforming growth factor-beta (TGFβ) and interleukin-6 (IL6), which activate downstream signaling pathways leading to enhanced tumor cell proliferation, migration, and invasion." (PMID 38999251, 2024). "Research shows that frailty can lead to elevated levels of IL-6, C-reactive protein (CRP), and TNF-α in the tumor microenvironment." (PMID 39042180, 2024). "Among other predictive markers, IL-6 proved to be significant in a multivariate analysis adjusting for known factors (i.e., smoking, COPD, age, or tumour histotype)." (PMID 38610929, 2024). "The tumor immune microenvironment (TME) includes immune cells, cytokines like IL-6 and TNF-α, and regulatory factors, all of which contribute to tumor progression and metastasis." (PMID 39896817, 2024). "We identified pro-inflammatory cytokines (IL1A, IL1B, IL6), and chemokines (CCL3, CXCL2, CXCL3) that promote inflammation-promoted neoplasia." (PMID 38529274, 2024). "We found that the expression of IL-6 was lower, while the expression of STAT3 was higher in tumor tissues using mIF." (PMID 38881895, 2024). "Efforts have also been made to develop therapeutic strategies to counteract specific cytokines' inflammatory and tumor-promoting effects, such as TNF, IL-1β, and IL-6." (PMID 38801637, 2024). "S100A8/A9 can interact with PDAC cells and CAFs, leading to the expression of various pro-inflammatory cytokines (such as IL-6, IL-8, and TNF-α), while knockout of CD74 delay the growth of tumor." (PMID 38167055, 2024).
tumor (continued). "The tumor-derived factors including macrophage colony-stimulating factor (MCSF), COX-2, interleukins like IL-6, 13, 17 promote the expansion of MDSCs exhibiting increased expression of TGF-β." (PMID 39497943, 2024). "Specifically, the activation of AhR triggers the up-regulation of IL-6, which subsequently mediates signal transducer and activator of transcription 3 (STAT-3) signaling, promoting the expression of IDO-1 in tumor cells." (PMID 39062529, 2024). "Meanwhile, it can also recruit MDSCs (myeloid-derived suppressor cells) by activating NF-κB pathway, which promotes the secretion of IL-6 and TNF-α to induce tumor proliferation." (PMID 38444674, 2024). "In the present study, by integrating scRNA-seq data with TCGA HNSCC dataset, we identified five enriched pathways, including IL6/IL6R and CCL2/CCR2 signaling, within NK cells and tumor cells in the HPV − HNSCC cohort compared to the HPV + counterpart." (PMID 38468260, 2024). "It has also been reported that interleukin 8 (IL-8), interleukin 6 (IL-6), and VEGF expressed on the surface of exosomes, affect the Wnt signaling pathway to mediate tumor invasion and metastasis." (PMID 38633106, 2024). "Mechanically, TAMs interact with bone marrow stromal cells(BMSCs) to acquire the function of secreting IL-6 and IL-10, poorly secreting IL-12 and TNF-α, which are suitable for tumor growth." (PMID 38464531, 2024). "IL6 can reverse the SLC7A11 knockout effect through the JAK2/STAT3 pathway, inhibit ferroptosis and promote tumor resistance." (PMID 39544949, 2024). "Tumour cell death was accompanied by the release of IFN-β, TNF-α, and IL-6 (attributed to cGAS/STING activation in the surrounding immune milieu following immunogenic cell death), all of which are drivers of anti-tumour inflammation." (PMID 39403376, 2024). "In co-culture with tumor cells and monocytes, stCAR T cells exhibited anti-tumoral activity and potent release of CRS-related cytokines (IL-6, IFN-γ, TNF-α, GM-CSF, IL-2, IL-10)." (PMID 38514793, 2024). "In contrast, tumor cells in a persistent senescent state can release SASP factors, such as the proinflammatory cytokines IL-1α, IL-6 and IL-8, to mediate tumor progression in neighboring cells." (PMID 39342176, 2024). "Single-cell transcriptome analysis also showed the expression of IL-6, gp-130, CRP and JAK2 was lower in tumor tissues compared with normal tissues." (PMID 38881895, 2024). "Interleukin-6 (IL-6), interleukin-1 (IL-1), and TNF-α, among others, are produced by tumor cells and stromal cells." (PMID 38612357, 2024). "In both the CD8 TIL-tumor coculture and the CD8 CEA-CAR coculture, increased levels of TNF were observed, as well as increased IL-6 and AREG levels in the anti-CEA-CAR system." (PMID 38226976, 2024). "In vitro and in vivo studies illustrated that IL-1β is a key mediator of IL-6 induction via activation of the NF-κB pathway, subsequently activating the IL-6/JAK/STAT3 cascade and promoting tumor growth and aggressiveness." (PMID 38103126, 2024). "Mechanistically, RK reduced circulating interleukin‐6 (IL‐6) concentrations from 334 ± 151 to 164 ± 123 pg/mL (P = 0.047) in C26 and from 93 ± 39 to 35 ± 6 pg/mL (P = 0.0053) in CHX207 tumour‐bearing mice." (PMID 38302863, 2024). "In tumor biology, interleukins as IL-1b, IL-8, IL-6 promote cell proliferation and epithelial-mesenchymal transition (EMT), but IL-6 also influences cell cycle arrest and immune clearance of damaged cells, as well as CCL2 and CXCL1." (PMID 38175424, 2024). "Inflammatory factors, particularly IL-6, can activate the STAT3/NF-κB pathway in both stromal and tumor cells." (PMID 39309424, 2024). "These interactions trigger the release of growth factors, cytokines (such as IL-6, IL-8), and angiogenic factors (VEGF), which promote tumour growth, osteoclast activation, and their proliferation, with the subsequent osteolysis." (PMID 40757720, 2024).
tumor (continued). "This immunosuppressive environment is controlled by the tumor through the release of cytokines and other soluble factors such as TNF-α, IL-6, TGF-β, and IL-10, involved in cancer progression." (PMID 39247827, 2024). "It is known that the IL-6-induced JAK/STAT3 signaling pathway drives the proliferation and survival of tumor cells." (PMID 38182653, 2024). "Remarkably, the supernatant of tumor monocytes was able to induce a higher expression of CRC EGC marker genes (Lcn2, Timp1, Ccl2, and Il6) compared to control BM-derived monocytes in an IL-1R-dependent manner." (PMID 39030280, 2024). "Various inflammatory cytokines such as tumor necrosis factor α (TNF-α), interleukin-6 (IL-6), interleukin-1 α (IL-1α), and interferon-γ (IFN-γ), produced by either tumor or host cells, can serve as triggers for these pathways." (PMID 38921029, 2024). "In TME, CAF-derived cytokines, including IL-6, IL-8 and CXCL-1, act as ligands for JAK/STAT signal cascade, some of which can also be secreted from tumour cells." (PMID 38926351, 2024). "IL‐6 also activates STAT3 promoter gene transcription through JAK, promoting cell proliferation and preventing cell apoptosis, leading to tumour formation." (PMID 38961677, 2024). "This process leads to the activation of pro-inflammatory pathways, including the production of cytokines such as interleukin-6 (IL-6) and tumor necrosis factor-alpha (TNF-alpha), which can promote tumor growth and metastasis." (PMID 39272881, 2024). "The high levels of ROS produced by mitochondrial dysfunction can stimulate tumor cells to release TNF-α, IL-6, and IL-1β, which attract suppressive immune cells and directly damage effector immune cells, reducing their activity." (PMID 39130746, 2024). "Tumor-induced cytokines such as TNF-α, interleukin 1 beta, and IL-6 contribute to the inhibition of albumin gene expression in cachexia." (PMID 38339365, 2024). "Lastly, CAFs promote tumor progression by remodeling the ECM and producing cytokines and growth factors, e.g., IL-6 and stromal cell-derived factor-1 (SDF-1), making them potential NP targets to improve immunotherapy efficacy." (PMID 39030582, 2024). "Tumor cells secreting factors such as IL-6, TGF-β, and IL-10 perpetuate an inflammatory environment that supports tumor growth and suppresses antitumor immune responses." (PMID 39664377, 2024). "As high IL-6, s-IL-6Rα, and s-gp130 predicted survival among the HPV(−) tumor patients, activation of both the classical and trans intracellular pathways seem to be associated with both increased HNSCC-caused and general mortality." (PMID 38672565, 2024). "In tumor-bearing mice, the combination of CSF3 and IL-6 cooperates to convert neutrophil precursors in the bone marrow into a pro-tumorigenic phenotype, while bone-marrow-derived neutrophils from mice lacking tumors have an anti-tumorigenic effect." (PMID 39338937, 2024). "Hypoxic tumor cells produce cytokines such as oncostatin, HMGB-1, TGF-β, or IL-6 to promote an alternative macrophage (M2) polarization and tumor progression." (PMID 39256888, 2024). "The cellular component of the innate immune system produces IL6 within the OC-TME, which plays a crucial role in sustaining a pro-tumorigenic environment, supporting immune evasion, and aiding tumor survival and metastasis." (PMID 39766086, 2024). "Recently, studies have found that IL-6 promotes normal macrophages to differentiate into M2 macrophages mediated by STAT3 and therefore supports tumor proliferation in gastric cancer." (PMID 38245798, 2024). "The study found that TFA can decrease the expressions of IL-6 and STAT3 via the IL-6/STAT3 pathway in Lewis ruffed tumor mice, thus suppressing tumor growth." (PMID 39215362, 2024). "For example, TAMs are known to produce IL-6, which promotes the expansion of CD44+ HCC cancer stem cells (CSCs) in vitro and xenograft tumour growth in vivo." (PMID 39684877, 2024).